SMAD4 (SMAD family member 4)
Diseases named in the same sentence as SMAD4 in open-access papers (continued):
Sharing a sentence is not in itself a finding about the gene and the disease.
tumor (continued). "One prognostic biomarker in CRC is the tumor suppressor SMAD4, the central node in the transforming growth factor‐beta (TGF‐β) superfamily." (PMID 34114372, 2022). "Nevertheless, our data showed that PDOs from tumor sites C, E, and F had a moderate expression of both CDX2 and SMAD4, whereas PDOs from tumor sites A, B, and D rarely expressed both proteins." (PMID 35853873, 2022). "Transcriptional regulation of human SMAD4, a key tumor suppressor deregulated in most gastrointestinal cancers, entails four alternative promoters." (PMID 35034624, 2022). "As expected, Smad4KO‐induced tumor cells’ hyper‐proliferation was inhibited by Smad4 re‐expression (KO+Smad4) in vitro." (PMID 35064757, 2022). "In 67 cases with SMAD4 expression at any site, the association of prognosis and clinicopathological factors with SMAD4 intensity was evaluated separately for the tumor invasion front and the central lesion." (PMID 36088360, 2022). "Acquisition of mutations, mainly affecting KRAS or tumor suppression genes (e.g., TP52, CDKN2A, and SMAD4), accelerates development of pancreatic ductal adenocarcinoma." (PMID 36421339, 2022). "The presence of well-known mutations reported in genes that commonly occur in EAC, known as driver mutations like ARID1A, CDKN2A, KRAS, APC, SMAD4, and PI3KCA, and a high tumor mutation burden (TMB) level makes EAC a highly heterogeneous disease." (PMID 35328735, 2022). "Collectively, the recent evidences suggest that Smad4 is a key player in regulating tumor progression and tumor suppression depends upon type and stage of malignancy." (PMID 35295334, 2022). "Further, Smad four knockdown in MDA-MB-231 resulted in the attenuation of EMT transition and bone metastasis thereby highlighting the role of Smad4 in both tumor suppression and progression." (PMID 35295334, 2022). "In all analyzed sample pairs but two, the portion of SMAD4–201 transcript was higher in tumor in comparison to non-tumor tissue, and the average increase was 20% (p = 0.001)." (PMID 35034624, 2022). "Normally, BMP acts through SMAD4 to exert tumor suppressive effects, but it can also signal in a SMAD4-independent manner." (PMID 36436127, 2022). "SMAD4 is an essential tumor suppressor gene that can mediate transforming growth factor-β superfamily signaling." (PMID 35853873, 2022). "DCC encodes for a nectrin-1 receptor and functions as a tumor suppressor gene with apoptotic ability, while SMAD4 regulates the TGF-β pathway to limit tumor growth and invasion." (PMID 35565354, 2022). "SMAD4 has been reported to function mainly as a tumor suppressor through cell cycle arrest, apoptosis, and differentiation." (PMID 36088360, 2022). "The other transcripts contributing to the total SMAD4 expression are dominant in non-tumor tissue and they should be further characterized, since their decrease and/or loss seems to be associated with carcinogenesis." (PMID 35034624, 2022). "Relative abundance of SMAD4–201 in total SMAD4 mRNA was analyzed using quantitative PCR in a set of permanent human colon cell lines and tumor and corresponding healthy tissue samples from patients with CRC." (PMID 35034624, 2022). "Here, the authors show that an antibody drug conjugate-like compound targeting both EGFR and HER2 overcomes gemcitabine resistance in PDAC preclinical models by mechanisms involving the tumour suppressor SMAD4." (PMID 36127339, 2022).
tumor (continued). "It has been also reported that SMAD4 has dual functions, in carcinogenesis via silencing and in tumor invasion/metastasis via signaling, depending on tumor stage." (PMID 36088360, 2022). "In this context, IL-8 induction by SMAD4 knock-down results in neutrophil recruitment into the TME via the IL-8 receptor CXCR2; these tumor-associated neutrophils (TAN), in turn, overexpress IL-8 when compared to peripheral blood neutrophils." (PMID 36289899, 2022). "The results above showed that the deletion of Smad4 in PDAC cells promoted tumor immunogenicity by increasing DNA damage‐induced IFN‐I signaling." (PMID 35064757, 2022). "Next, to elucidate the role of Smad4 in tumor growth in vivo, we subcutaneously inoculated equal numbers of WT or Smad4KO cells into syngeneic C57BL/6 (B6) mice and monitored the tumor growth." (PMID 35064757, 2022). "How this link between the glycolytic and mesenchymal phenotypes fits with the canonical function of SMAD4 as a mediator of TGF-β signalling and the more epithelial character of SMAD4-deleted tumours remains to be elucidated." (PMID 36088504, 2022). "Previously, our group reported that all cervical SCC tumours show nuclear pSMAD2 expression and cytoplasmic SMAD4 expression." (PMID 35756604, 2022). "Although Smad4 deletion in tumor cells enhances proliferation in vitro, the in vivo growth of Smad4‐deficient PDAC tumor is significantly inhibited on immunocompetent C57BL/6 (B6) mice, but not on immunodeficient mice or CD8+ cell‐depleted B6 mice." (PMID 35064757, 2022). "The results demonstrated that the combination treatment produced a significantly synergistic inhibitory effect on tumor cell growth, especially on SMAD4-defficient/gemcitabine-resistant AsPC-1 cells or xenografted tumors." (PMID 36127339, 2022). "To better delineate why ICI treatment results into variable responses, we employed another syngeneic mouse model of SCC, namely, the A223 tumor with Smad4 deletion, which has been characterized previously." (PMID 36330485, 2022). "In a series of patients with PDAC receiving downstaging therapy, patients with intact SMAD4 tumors had better treatment response and tumor regression scores." (PMID 35205719, 2022). "We also demonstrate that tumor tumor-intrinsic factors such as SMAD4 act as a barrier against tumor immune escape." (PMID 33674596, 2021). "Consistently with these observations, SMAD3 knockdown increased E-cadherin expression, downregulated Vimentin, and reduced cell migration cells in vitro, as well as prevented TGFβ-induced EMT in SMAD4-expressing tumor cells." (PMID 34680235, 2021). "The overall aim of the present study was to determine if copy number alterations of SMAD4 and CDKN1B in SINETs correlate with corresponding protein expression and can be linked to tumor initiation." (PMID 33509126, 2021).
tumor (continued). "SMAD4 is localized at the chromosome band 18q21; it functions as a tumor suppressor in the TGF‐β signaling pathway, thereby regulating cell proliferation, differentiation, morphogenesis, and apoptosis." (PMID 34014970, 2021). "The deletion of Smad4 and Pten by the Cre plasmid in the tumor was confirmed by PCR using specific primers." (PMID 34803491, 2021). "Exosomal miR-210 derived from HCC cells is internalized by endothelial cells, and promotes tumour angiogenesis through direct inhibition of the SMAD4 (SMAD family member 4) and STAT6 (signal transducer and activator of transcription 6) genes." (PMID 34066780, 2021). "For instance, TGFβ has been shown to be potently tumour suppressive in disease initiation as illustrated by the frequent mutations to signalling components, TGFβ-receptor-2 (TGFBR2), TGFBR1 and SMAD4 in human PDAC." (PMID 34638468, 2021). "By informatics analysis, we identified three tumor suppressor genes: DACH1, PCDH10 and SMAD4, all of which were negatively associated with FOXM1 and validated as functionally relevant targets of miR-552." (PMID 33867818, 2021). "MIR22HG exerted its tumor suppressive effects through competitively binding to SMAD2 and blocking the association between SMAD4 and SMAD2 in colorectal cancer cells." (PMID 33511320, 2021). "Most notably, inactivation of SMAD4 accelerated KRAS KO tumor development in mice in a statistically significant manner and fully restored the epithelial phenotype of KRAS KO tumors." (PMID 33674596, 2021). "SMAD4 is a tumor suppressor gene that regulates cell proliferation, distinction, and extracellular matrix production." (PMID 33825073, 2021). "In the initial phase of tumor formation, SMAD4 has a mainly positive effect in promoting the development and antitumor activity of NK cells." (PMID 33627136, 2021). "DACH1 methylation leads to downregulation of TGF-β or decreased expression of Smad4, which is related to increased depth of invasion, late tumor stage, and poor differentiation." (PMID 34568328, 2021). "Further analysis indicated that lower m6Sig score also correlated with greater tumor mutation loads, PD-L1 expression, and higher mutation rates in SMGs (e.g., PIK3CA and SMAD4)." (PMID 33500720, 2021). "This study measured activins and follistatin in malignant colon tissues and the results were compared between the early and late clinical stages of cancer according to tumour sidedness and Smad4 expression." (PMID 34867090, 2021). "On the other hand, in advanced PDAC tumors, TGF-β is reported to promote tumor progression, by a non-SMAD4 dependent signaling, via the activation of the WNT/β-catenin axis, known to regulate numerous biological and pathological processes." (PMID 34440587, 2021). "We validated the interactions of circATRNL1/miR‐378 and miR‐378/Smad4, and a mouse tumor xenograft model was employed to assess the effect of circATRNL1 on tumor growth and metastasis in vivo." (PMID 33372356, 2021). "Although TGFβ has a clearly dual function in tumor prevention and carcinogenesis, approximately half of PDAC patients demonstrate a loss of the TGFβ effector SMAD4." (PMID 34680235, 2021). "In summary, our results clarify the tumor suppressor roles of MTX2-6/miR-574-5p/SMAD4 axis in the progression of ESCC and provide emerging therapeutic targets for ESCC patients." (PMID 33869216, 2021). "The TGF-β/SMAD4 signaling pathway plays a tumor suppressive role in early stages of disease, mainly by inducing cell cycle arrest and apoptosis." (PMID 34880877, 2021).
tumor (continued). "Of note, a recent study showed a previously unappreciated function for tumour cell-intrinsic SMAD4 by promoting anti-tumour immunity in PDAC." (PMID 33862582, 2021). "As shown, the levels of lnc-UTGF, SMAD2, and SMAD4 were significantly higher in HCC tissues compared with the matched adjacent non-tumor liver tissues." (PMID 34785655, 2021). "Using immunohistochemistry and FISH, we evaluated the protein staining intensity of SMAD4 and p27 in relation to gene copy number status on consecutive tumor sections." (PMID 33509126, 2021). "This suggests that the TGFβ-induced expression of PD-L1 on LY2 tumor cells is dependent on Smad4-mediated canonical TGFβ signaling." (PMID 34433873, 2021). "We confirmed that CAF lines are free of tumor cells that would harbor Smad4 deletion, express Cre transcript, and KRASG12D protein." (PMID 34527666, 2021). "Exosomal miR-210-3p secreted by HCC tumour cells and delivered also in endothelial cells targeting SMAD4 (SMAD family member 4) and STAT6 (signal transducer and activator of transcription 6) resulted in enhanced angiogenesis." (PMID 34064331, 2021). "The loss of SMAD4 leads to extensive signaling alterations in PDAC cells, including the disruption of TGFβ-induced cell cycle arrest, enhanced tumor cell migration, and reduced chemo- and radiosensitivity." (PMID 34680235, 2021). "The role of TGF-beta/SMAD4 in governing tumor cell antigenicity and immune signaling is of particular interest." (PMID 33674596, 2021). "Accordingly, the loss of SMAD4 leads to extensive metabolic reprogramming in PDAC cells, which appears to alter tumor cell sensitivity to mitochondrial-targeted therapy." (PMID 34680235, 2021). "Multivariable analysis revealed solid tumor morphology, tumor SUVmax, clinical stage, SMARCA4 and SMAD4 alterations were independently associated with pathologic LN metastasis." (PMID 34290393, 2021). "SMAD4 is an established tumor suppressor gene located in chromosome band 18q21, and one of the most commonly destroyed gene in cancer among SMAD family genes." (PMID 34301194, 2021). "Another tumor suppressor gene is SMAD4 which shows critical role in the TGF-β signaling pathway as well." (PMID 33825073, 2021). "Nuclear SMAD4 expression and tumor size showed independent poor DSS, with hazard ratios of 3.10 and 1.13 and P values 0.013 and 0.034, respectively." (PMID 34012911, 2021). "Crosstalk between the WNT/β-catenin pathway and TGF-β/SMAD4 pathway in the tumor immune microenvironment was thus implied." (PMID 34335594, 2021). "Genetic alterations of SMAD4 are also seldomly found in advanced PanIN lesions and represent the final step to complete tumor development." (PMID 34944807, 2021). "Analysis of TMA-based IHC staining demonstrated that expression of SMAD4 was localized to the nucleus and cytoplasm of tumor cells." (PMID 34012911, 2021). "SCC is commonly associated with dysregulated TGFβ signaling, with 69% of human patients exhibiting TGFβRII downregulation and 35% exhibiting SMAD4 deletions in tumor epithelial cells, which is critical for canonical TGFβ signaling." (PMID 34433873, 2021). "In conclusion, we found that SMAD4 mutation was associated with poor prognosis in CRC, but has nothing to do with MSI status, BRAF status or tumor grade." (PMID 34301194, 2021). "Two tumor suppressor genes and corresponding proteins i.e. SMAD4, and CDKN1B, were further characterized using a tissue microarray (TMA) with 846 SINETs." (PMID 33509126, 2021). "Accordingly, ERK is required for TGFβ-induced EMT in non-malignant pancreatic ductal epithelial cells, early neoplastic epithelial cells, and SMAD4-expressing tumor cells." (PMID 34680235, 2021). "SMAD4 is the only common SMAD in TGF-β signaling that usually impedes immune cell activation in the tumor microenvironment." (PMID 34017344, 2021).
tumor (continued). "Selective deletion of Smad4 in NK cells impairs tumor cell rejection, promotes tumor cell metastases, and impedes NK cell homeostasis and maturation." (PMID 34017344, 2021). "Accordingly, SMAD4 promoter was mostly unmethylated (i.e., active) and possibly exerting its tumor suppressor role to prevent recurrence and metastasis in these patients." (PMID 34571856, 2021). "On the level of tumor burden analysis, the level of Smad4 in patients with higher-grade stages was lower than that of patients with lower-grade stages." (PMID 33794845, 2021). "EV-derived miR-210 released by hepatic tumor cells is transferred into endothelial cells and leads to tumor angiogenesis, inhibiting SMAD4 (mothers against decapentaplegic homolog 4) and signal transducer and activator of transcription 6 (STAT6) expression." (PMID 34207985, 2021). "In this study, our finding that Smad4 inactivates the PAK3-JNK-Jun pathway in advanced or metastatic lung cancer provides a function for the tumor-suppressive Smad4." (PMID 34381046, 2021). "We also identified p15INK4b, a cell cycle inhibitor, as an important target for TGF-β/SMAD4-induced tumor-suppressor functions." (PMID 34070531, 2021). "Analyzing the tumor-induced neutrophils recruitment mechanism, it was revealed that TANs are recruited via the CXCL1/8-CXCR2 axis and the loss of SMAD4." (PMID 33917620, 2021). "The loss of oncogenic RAS and SMAD4 signals synergistically upregulate the abnormal expression of EGFR and ERBB2, leading to the development of neoplasm and the metastasis and spread of the primary tumor." (PMID 34301194, 2021). "In summary, our study clarified the tumor suppressor roles of MTX2-6/miR-574-5p/SMAD4 axis in ESCC, which provided prognostic markers and promising therapeutic targets for ESCC patients." (PMID 33869216, 2021). "These alterations are already found in early precursor lesions such as PanIN, following inactivation of tumor suppressor genes such as CDKN2A, TP53m or SMAD4, which in turn contribute to an enhancement of the tumor stroma." (PMID 34944807, 2021). "Knock-down of KDM3A, KLF5, SMAD4 or EGFR in tumour cells influenced the immune TME and re-sensitized tumours to combination immunotherapy." (PMID 33671588, 2021). "SMAD4 mediates signaling of transforming growth factor beta and bone morphogenic protein ligands, and it is a well-defined tumor suppressor in pancreatic and colon cancer." (PMID 34290393, 2021). "Next generation sequencing (NGS) confirmed the tumor was microsatellite stability (MSS), and a total of 6 gene mutations, TSC2, CREBBP, HIST1H3I, MAP2K4, SMAD4, and STK11 were detected." (PMID 34880877, 2021). "It is worth to note that while silencing of either Smad2 or Smad3 led to accelerated c-Myc tumor growth, silencing of Smad4 demonstrated the most significant tumor acceleration phenotype." (PMID 33608500, 2021). "Both SMAD4 and PTEN have been revealed a closely linked in the regulation of tumor infiltration and distant metastasis." (PMID 33825073, 2021). "Given the diametrical change in the response to BMP signals following the loss of SMAD4, it will be interesting to investigate the response of tumor cells to stromal Hh signaling in CRCs which retain SMAD4 versus those that have lost SMAD4 expression." (PMID 33498528, 2021). "The biological consequence of SMAD4 P356L was reproduced by SMAD4 suppression using siRNA because SMAD4 functions as a tumor suppressor." (PMID 35008475, 2021).